SLC7A11 (solute carrier family 7 member 11)
Diseases named in the same sentence as SLC7A11 in open-access papers (continued):
Sharing a sentence is not in itself a finding about the gene and the disease.
breast cancer (continued). "Generally, GPX4 expression is upregulated in breast cancer, closely related to the increased expression of the two subunits of the cysteine/glutamate antiporter (xCT), SLC7A11 and SLC3A2." (PMID 39664391, 2024). "Here, we showed that KCTD10 knockdown increased the viability and clonogenic survival of breast cancer cells by stabilizing SLC7A11 to confer resistance to ferroptosis, which was abrogated by either SLC7A11 knockdown or treatment with a ferroptosis inducer." (PMID 38959043, 2024). "Biologically, USP18 knockdown suppresses, whereas KCTD10 knockdown promotes growth of breast cancer cells via reducing or increasing SLC7A11, respectively." (PMID 40440083, 2024). "Using the example of MDA-MB-231 breast cancer cells, it was shown that 18-β-glycyrrhetinic acid (GA) suppressed the expression of SLC7A11 of the xc- system, reduced the level of GSH, inhibited GPX activity and induced ferroptosis." (PMID 38785550, 2024). "SLC7A11 gene copy number and mRNA expression were evaluated using the Molecular Taxonomy of Breast Cancer International Consortium (METABRIC) cohort (n = 1,980) and Breast Cancer Gene Expression Miner (n = 4,712)." (PMID 38073087, 2024). "CircBGN directly binds to OTUB1 and SLC7A11, enhancing OTUB1-mediated SLC7A11 deubiquitination to inhibit ferroptosis in breast cancer." (PMID 37686142, 2023). "SLC7A11 (xCT), SLC3A2 (xCT), and GPX4 expression have been reported to be elevated in a subset of TNBC breast cancer models predicting response to erastin (xCT inhibitor) and RSL3 (GPX4 inhibitor)." (PMID 37596261, 2023). "In the same way, metformin reduces the protein stability of SLC7A11 by inhibiting its acylation process from inducing ferroptosis in breast cancer cells." (PMID 37373183, 2023). "High expression of SLC7A11, a critical regulator of ferroptosis, predicts poor prognosis in breast cancer." (PMID 38027016, 2023). "The cystine-glutamate antiporter xCT (SLC7A11) is a potential target for immunotherapy in breast cancer." (PMID 37880659, 2023). "The two amino acid transporters SLC7A5 and SLC7A11 are considered essential for the growth of breast cancer cells in a cell-dependent manner." (PMID 37754258, 2023). "This study found that SLC7A11 is highly expressed in cancers such as breast cancer, LUSC, LUAD, and gastric cancer." (PMID 37880315, 2023). "SLC7A11, a key component of the cystine–glutamate antiporter, is another UFMylation substrate with important functions in breast cancers." (PMID 37947621, 2023). "Targeting SLC7A11 has yielded promising results in hepatocellular carcinoma, breast cancer, and bladder cancer." (PMID 37460542, 2023). "DKK1 can be used upstream of SLC7A11 to increase the expression of SLC7A11 in breast cancer cells and protect metastatic cancer cells from lipid peroxidation and iron-related death." (PMID 37829798, 2023). "For example, SLC7A11, a key gene for disulfidptosis, while promoting disulfidptosis in cancer tissues, is highly expressed in multiple tumors such as breast cancer, pancreatic cancer, and ovarian cancers, promotes cancer progression and metastasis." (PMID 38097783, 2023). "18F-5-fluoroaminosuberic acid, a synthetic amino acid substrate of SLC7A11, exhibited tumor uptake in three breast cancer cell lines (MDA-MB-231, MCF-7, and ZR-75-1), with the highest uptake observed in MDA-MB- 231, the TNBC cell line." (PMID 37754258, 2023). "In contrast to ACS1 and ERα UFMylation, SLC7A11 UFMylation inhibits metformin-induced breast cancer cell ferroptosis." (PMID 37947621, 2023). "High expression of xCT, which is the member 11 of solute carrier family 7 (SLC7A11), was commonly along with increased levels of ROS and sensitivity to glucose deprivation in breast cancer cells." (PMID 35096052, 2022). "It is worth noting that decreased SLC7A11 level is related to increased methionine dependence of breast cancer cells and drug resistance of gastric cancer." (PMID 35123415, 2022).
breast cancer (continued). "Virus-like particle immunotherapy or vaccines against SLC7A11 have been developed and shown to reduce the metastatic potential of breast cancer cells." (PMID 36105219, 2022). "Adequate cystine supplementation in tumour-bearing mice with breast cancer increased the expression of SLC7A11 and promoted the synthesis of GSH." (PMID 35804831, 2022). "Further RNA sequencing analysis showed that SLC7A11 expression was upregulated in breast cancer tissues with brain metastases, suggesting a role for SLC7A11 in breast cancer metastasis." (PMID 36105219, 2022). "A strong positive correlation between FGFR4 expression and SLC7A11 or FPN1 expression was discovered in HER2-positive breast cancer." (PMID 35562334, 2022). "Binding of FINS targeting GPX4 or SLC7A11 to RT can sensitize breast cancer cell lines or xenografts to radiation by enhancing ferroptosis sensitivity." (PMID 36467032, 2022). "For example, miR-26b-5p, down-regulated in breast cancer, induces breast cancer cell apoptosis via targeting SLC7A11." (PMID 35721153, 2022). "SLC7A11 has also been shown to be important in breast cancer stem cell maintenance and correlates with poor prognosis in patients." (PMID 35280777, 2022). "Metformin, a potential anti-cancer agent, induces ferroptosis in breast cancer by reducing the protein stability of SLC7A11." (PMID 36009223, 2022). "Drug-resistant breast cancer cells are dependent on GPX4 and SLC7A11, which means they are vulnerable to ferroptosis caused by GPX4 and SLC7A11 inhibition." (PMID 36105219, 2022). "Meanwhile, SLC3A2 has been reported to bind with cystine transporter xCT/SLC7A11, which has an essential function in the growth of ER- breast cancer cells." (PMID 35501367, 2022). "Administration of SLC7A11 targeting miR-5096 induces ferroptosis in human breast cancer cells and lidocaine treatment results in ferroptosis and ROS induction in both breast and ovarian cancer cells." (PMID 35280777, 2022). "Virus-like particles (AX09-0M6) displaying the 6th extracellular loop of SLC7A11 common to both mouse and human SLC7A11 disabled the self-renewal ability of breast cancer stem cells." (PMID 35280777, 2022). "For instance, breast cancer cell lines seem to depend on SLC3A2 which encodes for the heavy chain subunit of the cystine-glutamate antiporter (xCT system), along with SLC7A11." (PMID 35912247, 2022). "Insulin-like growth factor-I (IGF-I) regulates cystine uptake and redox status in ER+ breast cancer cells by activating SLC7A11 expression." (PMID 36552652, 2022). "The ectopic overexpression of SLC7A11 inhibits miR-5096-mediated ferroptosis and diminishes antitumor effects in breast cancer." (PMID 36467032, 2022). "Glutamate release by SLC7A11 promotes tumor invasion through the upregulation of membrane type 1 metalloprotease and basement membrane disruption in breast cancer cells." (PMID 36552652, 2022). "The hsa-miR-5096 was reported as a potential tumor suppressor miRNA capable of inhibiting the proliferation, migration, and invasion of breast cancer cells in vitro by targeting the SLC7A11 gene, which is related to ferroptosis resistance." (PMID 35774498, 2022). "MiR-382-5p was found to directly interact with SLC7A11 in ovarian and breast cancer cells, whereas miR-382-5p was downregulated and SLC7A11 was upregulated." (PMID 35755805, 2022). "Breast cancer clinical data also showed that higher SLC7A11 expression was correlated with worse survival outcomes in lymph node-positive/metastatic patients but not in the lymph node-negative or overall patient population." (PMID 35296660, 2022). "Low regulation of SLC7A11 or cystine deprivation induces ROS-induced overexpression of P-gp in breast cancer cells and drug resistance." (PMID 36552652, 2022).
breast cancer (continued). "The cystine-glutamate antiporter xCT, encoded by the SLC7A11 gene, which imports cystine in exchange with glutamate, is a potentially new target for breast cancer therapy, being involved in tumor cell redox balance and resistance to therapies." (PMID 36359363, 2022). "These cells lines are SLC7A11-high and import more cystine than other breast cancer subtype cell lines." (PMID 35280777, 2022). "Lidocaine promotes ferroptosis in ovarian and breast cancer cells by enhancing miR-382-5p and down-regulating SLC7A11 expression." (PMID 35805124, 2022). "Downregulation of SLC7A11 or cystine deprivation significantly enhanced ROS-induced overexpression of P-gp in breast cancer cells and the resistant subline derived from them." (PMID 35804831, 2022). "The miR-382-5p expression was down-regulated but SLC7A11 expression was up-regulated in clinical ovarian and breast cancer samples." (PMID 34122108, 2021). "We also examined the inhibitory efficiency of metformin against SLC7A11 in other breast cancer cells." (PMID 34162423, 2021). "NRF2 was found to increase not only the expression of the SLC7A11 but also the activity of xCT in breast cancer cells." (PMID 33922165, 2021). "The product of the SLC7A11 gene, xCT, is a transmembrane protein that is overexpressed in cancer stem cells and is a target in breast cancer therapy." (PMID 33632278, 2021). "From the perspective of post-transcriptional modification, accumulating evidence demonstrates that SLC7A11 mRNA is derepressed by decreased miR-26b in human breast cancer and miR-375 in oral squamous cell carcinoma." (PMID 34722314, 2021). "MiR-382-5p/SLC7A11 axis was involved in lidocaine-mediated inhibition of ovarian and breast cancer cell proliferation in vitro." (PMID 34122108, 2021). "We found the SLC7A11 expression was significantly negatively correlated with the prognosis of patients with breast cancer." (PMID 34162423, 2021). "The expression of both SLC7A11 and SLC3A2 subunits can be a marker for xCT function and selenoprotein production capacity of breast cancer cells." (PMID 33672555, 2021). "SLC7A11 is highly expressed in many types of tumors such as acute myeloid leukemia, breast cancer, colorectal cancer, hepatocellular carcinoma, glioma, etc., and its high expression is associated with poor prognosis of patients with cancers." (PMID 33672555, 2021). "The results showed that KLF4 and SLC7A11 were positively correlated in basal-like breast cancer cells." (PMID 34040532, 2021). "Reduction of the intracellular GSH in response to SLC7A11 inhibition with erastin sensitizes breast cancer cells to γ-radiation by induction of complex DNA damage." (PMID 33401748, 2021). "We find that GPX4 is strongly upregulated in a subset of breast cancer tissues compared to matched normal samples, and that this is tightly correlated with the increased expression of the xCT subunits SLC7A11 and SLC3A2." (PMID 33672555, 2021). "Many studies have indicated that ferroptosis also mediated cell death in breast cancer by SLC7A11, which implied the important role of SLC7A11 in regulating the ferroptosis of breast cancer." (PMID 35252218, 2021). "Excluding unavailable SLC7A11 expression value, 1,104 breast cancer samples including 217 high expressions (19.66%) and low 887 expressions (80.34%) were extracted for further study." (PMID 35252218, 2021). "The miR-382-5p expression was down-regulated but SLC7A11 expression was up-regulated in clinical ovarian cancer tissues (n = 38) and breast cancer (n = 50) tissues compared with the adjacent tissues." (PMID 34122108, 2021). "Our study found that SLC7A11 was correlative to survival in breast cancer and high expression implied poor prognosis." (PMID 35252218, 2021). "Vaccines targeting SLC7A11 have been developed and demonstrated to protect mice from mammary cancer metastases." (PMID 33292585, 2020).
breast cancer (continued). "RNA sequencing analysis has revealed that SLC7A11 is upregulated in brain metastatic breast cancer tissues, implying a role for SLC7A11 in breast cancer metastasis." (PMID 33292585, 2020). "Chemotherapy in breast cancer induces HIF1α-dependent glutathione biosynthesis by enhancing the expression of the cystine transporter xCT (SLC7A11) and the regulatory subunit of glutamate-cysteine ligase (GCLM)." (PMID 32914752, 2020). "In contrast, signal transducer and activator of transcription (STAT) 3/STAT5 and miR-26b are negative regulators that inhibit SLC7A11 expression in breast cancer." (PMID 29562706, 2018). "In breast cancer cells, SLC7A11 was shown to be upregulated in tumorspheres with cancer stem cell features and to affect pulmonary metastasis." (PMID 29562706, 2018). "18F-5-fluoroaminosuberic acid, a synthetic amino acid substrate of SLC7A11, exhibited tumor uptake in three breast cancer cells lines (MDA-MB-231, MCF-7, and ZR-75-1), with the highest uptake observed in MDA-MB-231, a TNBC cell line." (PMID 29562706, 2018). "(G) SLC7A11 mRNA expression data from the CCLE is shown for breast cancer cell lines reported to be CB-839 resistant (IC50 >1 μM) or CB-839 sensitive (IC50 <1 μM)." (PMID 28826492, 2017). "Nrf2 expression is positively correlated with SLC7A11 expression across 59 breast cancer cell lines (R=0.5688), as well as all 947 cancer cell lines (R=0.4306) in the CCLE expression data." (PMID 28429737, 2017). "We chose two breast cancer cell lines, Hs578T and SK-BR-3, as representative of high and low SLC7A11 expressing cell lines, respectively." (PMID 28429737, 2017). "We show that, through its effect on SLC7A11 levels, Nrf2 is also a factor that can regulate glutamine metabolism and nutrient flexibility in some breast cancer cells." (PMID 28429737, 2017). "We found that genes related to OXPHOS were enriched in the low SLC7A11-expressing groups, especially in lung (P value=0.018) and breast cancer cell lines (P value=0.039)." (PMID 28429737, 2017). "xCT/SLC7A11 was expressed in three CB-839 resistant breast cancer cell lines, all of which had low baseline expression of this transport system: MCF7, MDA-MB-468 and AU565." (PMID 28826492, 2017). "In human breast cancer, downregulation of miR-26b can suppress cell apoptosis by targeting SLC7A11 and promote cellular growth by binding to PTGS2." (PMID 26204489, 2015). "miR-26a/b have also been reported to induce cell apoptosis by targeting MTDH, EZH2 and SLC7A11 in breast cancer cells and by targeting SODD in melanoma cells." (PMID 24565101, 2014). "Importantly, malignant breast cancer tissues exhibited higher protein levels of SLC7A11 and SLC3A2 compared to benign breast tissues, indicating a positive association of SLC7A11 and SLC3A2 levels with poor prognosis in breast cancer patients." (PMID 39833180, 2025). "Additionally, metformin can reduce the protein stability of SLC7A11 in breast cancer cells by inhibiting its UFMylation, leading to increased intracellular Fe2+ and lipid ROS levels, thereby inducing ferroptosis." (PMID 39973065, 2025). "Endocrine resistant ER+ breast cancer has elevated levels of SLC7A11 and SLC3A2." (PMID 39833180, 2025). "Further studies revealed that pretreatment of TNBC cells with niclosamide reduces the protein expression of SLC38A5 and SLC7A11, induces oxidative stress, lipid peroxidation, and ferroptosis, and significantly suppresses breast cancer growth in mouse xenograft models." (PMID 39973065, 2025). "Whether different SNVs in SLC7A11 exon regions could contribute to SLC7A11 expression and breast cancer initiation still needs to be studied." (PMID 40464376, 2025). "Additionally, miR-5096 has been reported to induce ferroptosis in human breast cancer cells by regulating the SLC7A11/xCT signaling axis." (PMID 41300440, 2025). "Thus, KCTD10 suppressed the survival of breast cancer cells by promoting ubiquitylation and degradation of SLC7A11 to induce ferroptosis." (PMID 38959043, 2024).
breast cancer (continued). "However, in this paper, we found expression of SLC7A11 in breast cancer cells transfected with si-circ_0022382 was decreased, which seems not to meet the common condition for disulfidptosis to occur." (PMID 39868374, 2024). "Thus, the combination of neddylation inhibitor MLN4924 and SLC7A11 inhibitor IKE would be a strategic choice for effective therapy against breast cancer." (PMID 38959043, 2024). "Indeed, downregulation of SLC7A11 promotes ROS-induced P-gp upregulation and drug resistance in breast cancer cell line." (PMID 38705513, 2024). "Our study here elucidated, at least in part, the mechanism by which some types of cancer, including breast cancer, adjust elevated SLC7A11 levels to meet a high requirement of cystine consumption, and subsequent cysteine-depleted microenvironment to ensure their survival." (PMID 38959043, 2024). "We next tested our working hypothesis that SLC7A11 inhibitor Erastin would sensitize breast cancer cells to MLN4924." (PMID 38959043, 2024). "Thus, in contrast to KCTD10, USP18 promotes the survival of breast cancer cells by stabilizing SLC7A11 to suppress ferroptosis." (PMID 38959043, 2024). "Thus, it appears that SLC7A11 accumulation by MLN4924 promoted cystine uptake to support breast cancer survival, which would compromise the anticancer activity of MLN4924." (PMID 38959043, 2024). "Furthermore, The expression level of SLC7A11 has a significant correlation with the expression of vimentin in breast cancer (r = 0.5088, p < 0.0001)." (PMID 39543094, 2024). "Additionally, metformin promotes ferroptosis in breast cancer cells by inducing UFMylation modification of SLC7A11, independently of the AMPK signaling pathway, revealing a novel anticancer mechanism of metformin." (PMID 39664391, 2024). "Finally, a bovine herpesvirus 4-based vector delivering full length SLC7A11 DNA protected mice from breast cancer metastases by targeting cancer stem cells." (PMID 35280777, 2022). "Most methionine-dependent breast cancer cell lines harbor a PIK3CA genomic mutation and decreased expression of SLC7A11, which is a gene that encodes a cystine transporter also known as xCT that is correlated with increased methionine dependency in breast cancer cells." (PMID 36432434, 2022). "Recently, it has also been shown that ferroptosis‐related genes such as GPX4 and SLC7A11, could serve as a novel biomarker for predicting the prognosis in breast cancer (another class of BRCA‐related cancer) patients." (PMID 36485069, 2022). "Metformin triggers ferroptosis via a reduction in the UFMylation of SLC7A11 in breast cancer." (PMID 35805124, 2022). "Nrf2 upregulates the expression and activity of SLC7A11 in breast cancer cells during oxidative stress, and promotes the survival of breast cancer cells from drugs and other treatments by antagonizing ROS, while Nrf2 expression is downregulated when ROS levels are reduced." (PMID 36105219, 2022). "In addition, Metformin a commonly used hypoglycemic drugs in clinical practice, was found to promote ferroptosis in breast cancer cells by inhibiting the UFMylation of SLC7A11 and the transcription of GPX4." (PMID 36105219, 2022). "Pharmacologically suppressing STAT3/5 activation could induce an adaptive, compensatory mechanism to protect breast cancer cells from ROS by activating SLC7A11 transcription and the action of system xCT." (PMID 35884471, 2022). "Overexpression of miR-5096 reduces mRNA and protein levels of SLC7A11 in breast cancer cells." (PMID 36105219, 2022). "SLC7A11 expression is significantly negatively correlated with the prognosis of patients with breast cancer, indicating that suppressing the negative regulator of ferroptosis may be a viable breast cancer therapy." (PMID 36355532, 2022).